HMGB1 (high mobility group box 1)
Diseases named in the same sentence as HMGB1 in open-access papers (continued):
Sharing a sentence is not in itself a finding about the gene and the disease.
renal fibrosis (continued). "The inhibition of the C3/HMGB1/TGF-β1 signaling pathway can inhibit the progression of renal fibrosis in DN." (PMID 33729484, 2021). "HMGB1 contributes to the development of many renal diseases including ischemic reperfusion injury, renal fibrosis due to chronic kidney disease, diabetic nephropathy, and granulomatous nephritis." (PMID 34341389, 2021). "To further investigate the inhibition of renal fibrosis and aortic calcification by exosomes, we assessed the characteristics of HMGB1 and SIRT6 in the mouse model of CKD." (PMID 33849640, 2021). "HMGB1 participates in the formation of renal fibrosis in the development of CKD through binding to TLR2 and RAGE." (PMID 30532765, 2018). "Upon binding to its cognate receptor, Hmgb1 would activate NFκB to transcribe inflammatory cytokines relevant to the initiation and progression of renal fibrosis." (PMID 26247732, 2015). "Together, those data indicate that renal fibrosis in CDK patients are also characterized by the enhanced HMGB1 expression along with its cytoplasmic translocation." (PMID 26247732, 2015). "However, the involvement of Hsp90α‐triggered HMGB1 regulation in the pathogenesis of renal fibrosis remains to be elucidated." (PMID 39566909, 2025). "In renal fibrosis caused by diabetic nephropathy, lncRNA ENSMUST00000147869 directly binds to the heat shock protein HSPA9, reduces its expression through ubiquitination degradation, and inhibits the interaction between HSPA9 and HMGB1, thereby inhibiting the development of renal fibrosis." (PMID 39113708, 2024). "A recent study suggested that olmesartan could alleviate renal fibrosis induced by SARS-CoV-2 envelope protein by regulating HMGB1 release and autophagic degradation of TGF-β1." (PMID 37803348, 2023). "In terms of kidney repair, HMGB1 released from pyroptotic renal tubular cells may amplify the inflammatory responses in macrophages, which contributes to renal fibrosis." (PMID 37284446, 2023). "Next, we investigated whether and how HMGB1 is involved in RLDC-induced renal fibrosis by using a well-established cell model." (PMID 37284446, 2023). "In this study, although the results from the study confirm that the activation of HMGB1/TLR2/4 contributes to the renal fibrosis process, the effect of the suppression of HMGB1 expression remains unclear and future experiments are needed." (PMID 36448056, 2022). "Therefore, the model enabled us to investigate the key factor in the progression of renal fibrosis in diabetic mice, which is much more intuitive to observe the effect of HMGB1 on the progression of renal fibrosis in DKD." (PMID 36448056, 2022). "Collectively, these results suggest that TGF-beta-mediated NLRP3 inflammasome activation may cause the release of HMGB1 and an increase in Gasdermin D cleavage in NRK-52E, thereby contributing to renal fibrosis in Ang II-induced CKD." (PMID 32117956, 2020). "HMGB1 induces EMT in lung and renal fibrosis, so we asked whether HMGB1 could mimic the effects of hypoxia on human NB cells." (PMID 26925422, 2016). "On the other hand, it is likely that some pro-fibrotic factors such as HMGB1 or HMGB1/TLR2 inhibition may be more important than TLR2 alone inhibition in interfering with renal fibrosis." (PMID 25284457, 2014). "Interestingly, it seems that TLR4 was probably the primary receptor for Hmgb1 in our model of UUO-induced renal fibrosis as Chop deficiency did not affect UUO-induced expression of TLR2 and RAGE but attenuated TLR4 by twofold." (PMID 26247732, 2015). "We demonstrated evidence that loss of Chop represses Hmgb1/TLR4 signaling following UUO induction, leading to repressed NFκB transcriptional activity along with suppressed IL-1β production, which then reduces TGF-β1 production and Pi3K/Akt activity to attenuate the development of renal fibrosis." (PMID 26247732, 2015). "To investigate the role of HMGB1 in RLDC-induced chronic inflammation and renal fibrosis, we analyzed HMGB1 expression." (PMID 37284446, 2023).
renal fibrosis (continued). "With the inhibition of HMGB1 release, olmesartan increased the level of HMGB1 in the cytoplasm, thus mediating the autophagic degradation of TGF-β1 and inhibiting renal fibrosis further." (PMID 37256223, 2023). "Therefore, targeted inhibition of HMGB1 may be a good strategy for improving renal fibrosis." (PMID 37781525, 2023). "Studies have shown that HMGB1-mediated RAGE activation results in the production of connective tissue growth factor (CTGF) and TGF-β, thereby promoting renal fibrosis in tubular epithelial cells." (PMID 38201260, 2023). "During the progression of DN disease, miR-92d-3p interacts with C3 to inhibit the activation of the C3/HMGB1/TGF-β1 pathway and EMT, thereby preventing the progression of DN renal fibrosis." (PMID 33729484, 2021). "RAGE is a ligand for several DAMPs, including high mobility group box 1 (HMGB1) and S100 proteins, which play an important role in renal fibrosis." (PMID 33117389, 2020). "Furthermore, E protein was documented to trigger the production of high-mobility group box 1 (HMGB1), which elicited proinflammatory response via TGF-β1/SMAD2/3 pathway, resulting in renal fibrosis." (PMID 38375473, 2024). "Olmesartan can inhibit the release of HMGB1 under stress significantly, thus inhibiting the excessive immune response and long-term inflammation, which promotes the development of CKD and ultimately leads to renal fibrosis." (PMID 37256223, 2023). "Stimulation using E protein could trigger HMGB1 release, induce renal damage and development into CKD and, finally, lead to renal fibrosis." (PMID 37256223, 2023). "Recent research found that less secretion of C3 appears to inhibit the activation of the High-Mobility Group Box 1 (HMGB1)-TLR4-p65 pathway signal pathway and the production of transforming growth factor-β (TGF-β1), thereby alleviating renal fibrosis in unilateral ureteral obstruction (UUO) mice." (PMID 36973754, 2023). "E protein stimulates the release of HMGB1, which can promote activation of the TGF-β1/Smad2/3 signaling pathway and trigger the inflammatory response, both of which contribute to renal fibrosis." (PMID 37256223, 2023). "Although the activation of HMGB-mediated TLR2/4 signaling has been analyzed in several mouse models of DKD, the correlation between HMGB1 activity and the progression of renal fibrosis is not well known." (PMID 36448056, 2022). "Thus, studying the relationship of miR-92d-3p with the C3/HMGB1/TGF-β1 pathway and EMT in DN renal fibrosis is necessary." (PMID 33729484, 2021). "Inhibition of HMGB1 release may alter macrophage phenotypes and ameliorated UUO-induced renal fibrosis." (PMID 34556635, 2021). "Inhibition of HMGB1 attenuated UUO-induced interstitial inflammation and renal fibrosis." (PMID 33117389, 2020). "HMGB1, the ligand of TLR4, can promote renal fibrosis by facilitating the M1 macrophage phenotype." (PMID 28416741, 2017). "Recent evidence has shown that HMGB1 can not only mediate injury and inflammation in acute renal IRI, but also participate in the release of TGF-β, the most potent cytokine promoting renal fibrosis, by tubular epithelial cells." (PMID 27690015, 2016). "Extracellular Hmgb1 thus bound to TLR4, and by which, it activated MyD88-NFκB pathway to enhance IL-1β expression, which in turn promoted TGF-β/Smad2/3 and Pi3k/Akt signaling to exacerbate renal fibrosis." (PMID 26247732, 2015). "In this investigation, we revealed that LM49 can effectively ameliorate renal fibrosis and filtration function in kidneys with unilateral ureteral obstruction (UUO)‐ and folic acid (FA)‐induced fibrosis, which is related to the suppression of HMGB1‐induced inflammation and TECs necrosis." (PMID 39566909, 2025).
renal fibrosis (continued). "Although the HMGB1 interaction with TLRs via stimulation of the NF-kB pathway has been analyzed in several mouse models of DKD, the correlation between HMGB1 level and the progression of renal fibrosis is not well known which slows the process of research on targeting HMGB1 for DKD therapy." (PMID 36448056, 2022). "HMGB1 can bind to cell surface receptors (such as the receptor of advanced glycosylation end-product [RAGE] and toll-like receptor 4) and may play an important role in promoting TGF-β1 production in DN and renal fibrosis." (PMID 33729484, 2021). "Because HMGB1 has been found to participate in the release of TGF-β by renal tubular epithelial cells and because TGF-β is the most prominent pro-fibrosis cytokine in the development of renal fibrosis, its expression in the kidneys was assessed by Western blot." (PMID 27690015, 2016).
systemic inflammatory response syndrome (36 papers, 2007 to 2025). SIRS is a serious condition related to systemic inflammation, organ dysfunction, and organ failure. "Thus, it was suggested that the serum peak HMGB1 concentrations were associated with the duration of the systemic inflammatory response syndrome and postoperative pulmonary dysfunction." (PMID 22283426, 2012). "HMGB1 correlates with pancreatic necrosis, systemic inflammatory response syndrome, and ICU transfer." (PMID 40941648, 2025). "Proinflammatory cytokines, including IL-1β, IL-6, and HMGB1, mediate the inflammatory response of immune cells and promote systemic inflammatory response syndrome." (PMID 34790828, 2021). "Increased levels of HMGB1 in circulation have also been documented in dogs with systemic inflammatory response syndrome and gastric dilation-volvulus." (PMID 34235204, 2021). "Previous studies have reported that LPS and HMGB1 can induce systemic inflammatory response syndrome (SIRS)." (PMID 32714569, 2020). "Actually, the administration of neutralizing antibodies against HMGB1 has been shown to successfully inhibit HMGB1 activity in various animal models and to limit systemic inflammatory response syndrome." (PMID 33062073, 2020). "A few reports are available on blood HMGB-1 concentrations in veterinary medicine, including dogs with systemic inflammatory response syndrome and dogs with lymphoma and canine prostate cancer." (PMID 28363279, 2017). "Beyond infections, HMGB1 has pathogenic roles during trauma and sterile inflammation, such as systemic inflammatory response syndrome (SIRS), where elevated levels in sera orchestrate key events including leukocyte recruitment and white blood cell (WBC) induction to secrete inflammatory cytokines." (PMID 27553758, 2016). "Several clinical studies have reported that serum HMGB1 levels are elevated in patients with infection and/or systemic inflammatory response syndrome, than in healthy control individuals." (PMID 21989210, 2011). "Therefore, in this work, we researched whether elevated concentrations of HMGB1 and S100A8 in children with acute lymphoblastic leukemia are associated with the presentation of systemic inflammatory response syndrome." (PMID 40868835, 2025). "While targeting early-phase cytokines gained only limited therapeutic effects, the administration of HMGB1 antagonists significantly improved the survival of systemic inflammatory response syndrome (SIRS) in rodents." (PMID 37223096, 2023). "Recombinant human thrombomodulin (rTM) significantly decreases serum HMGB1 levels and improves systemic inflammatory response syndrome (SIRS) in patients with hematological malignancies." (PMID 32660524, 2020). "Sepsis syndromes result from an exaggerated systemic inflammatory response characterized by a massive release of early mediators, such as TNF-α and IL-1β, and by the late mediator high-mobility group box 1 (HMGB1)." (PMID 29085368, 2017).
acute respiratory distress syndrome (34 papers, 2009 to 2025). Progressive and life-threatening pulmonary distress in the absence of an underlying pulmonary condition, usually following major trauma or surgery. "High mobility group box 1 (HMGB1) protein is one of the main risk factors for pediatric acute respiratory distress syndrome (PARDS) after living donor liver transplantation (LDLT)." (PMID 36944948, 2023). "HMGB1 was also reported to be associated with the pathogenesis of acute respiratory distress syndrome." (PMID 26067826, 2015). "Our group has previously shown that early increases of HMGB1 after polytrauma can predict organ failure such as acute respiratory distress syndrome (ARDS)." (PMID 39534595, 2024). "In SARS-CoV-2 infection, HMGB1 is thought to promote acute respiratory distress syndrome (ARDS) development and correlates with disease severity and mortality." (PMID 36675530, 2023). "For instance, a study in 2020 illustrated that, through targeting HMGB1 (high-mobility group box-1), a key cytokine that mediates the response to inflammation, injury, and infection, miR-574-5p evidently alleviated acute respiratory distress syndrome (ARDS)." (PMID 36671425, 2022). "Acute respiratory distress syndrome, a deadly complication of the SARS-CoV-2 and SARS-CoV-1, has been linked with HMGB1 production (74, –76)." (PMID 33658363, 2021). "Elevated circulating levels of AGEs and RAGE ligands, such as HMGB1 and S100 proteins, have been reported in severe COVID-19 cases and are associated with adverse outcomes, including acute respiratory distress syndrome (ARDS) and thromboinflammatory complications." (PMID 40981264, 2025). "Similarly, a study on patients with severe pneumonia and acute respiratory distress syndrome (ARDS) requiring mechanical ventilation identified day-1 HMGB1 levels as a critical and independent biomarker for ICU mortality." (PMID 40343200, 2025). "In addition, extensive studies have demonstrated that plasma HMGB1 level is a sensitive indicator of acute respiratory distress syndrome (ARDS)." (PMID 36944948, 2023). "Inhibiting HMGB1 or NET formation may mitigate pulmonary inflammation in acute respiratory distress syndrome and help treat inflammatory diseases such as diabetic wounds and COVID-19." (PMID 33925132, 2021). "High levels of extracellular HMGB1 play a critical role in impairing the clearance of invading pulmonary pathogens and dying neutrophils in the injured lungs of cystic fibrosis and acute respiratory distress syndrome (ARDS)." (PMID 34271850, 2021). "Accumulating evidence suggests that NLRP3-mediated alveolar macrophage (AM) pyroptosis and subsequent high mobility group box protein 1 (HMGB1) secretion play significant roles in the pathogenesis of acute respiratory distress syndrome (ARDS)." (PMID 40599023, 2025). "Various DAMPs, such as HMGB1, CIRP, HSP70, hyaluronan, and mtDAMPs contribute to the pathogenesis of bacterial pneumonia and its more severe form, acute respiratory distress syndrome (ARDS)." (PMID 34948277, 2021). "In acute respiratory distress syndrome (ARDS) mice, apoptotic neutrophil clearance is impaired and can be reversed by activating AMP-activated protein kinase (AMPK) or neutralizing high-mobility group box 1 (HMGB1)." (PMID 34630433, 2021). "RAGE expression was found to be upregulated in patients with acute respiratory distress syndrome (ARDS) and PGD, and while it can bind to a variety of ligands including advanced glycation end products, it has the highest binding affinity for HMGB1." (PMID 40725023, 2025). "PEVs that are HMGB1 positive are increased in COVID-19 and correlate positively with CRP levels, LDH expression, d-dimer, acute respiratory distress syndrome (ARDS), and patient WHO score." (PMID 35887184, 2022). "For example, NEAT1 was found to exacerbate acute lung injury (ALI) and acute respiratory distress syndrome (ARDS) by inducing alveolar epithelial cell injury and inflammation via HMGB1/RAGE axis." (PMID 34151707, 2021).
acute respiratory distress syndrome (continued). "The interaction of HMGB1 with RAGE activated the NF-κB and MAPK pathways, resulting in upregulation of HMGB1, RAGE, and other proinflammatory mediators, thus promoting the development of ALI or acute respiratory distress syndrome (ARDS)." (PMID 27563308, 2016). "In LPS-induced ALI mice models, lncRNA nuclear paraspeckle assembly transcript 1 (NEAT1) may induce alveolar epithelial cell injury and inflammation through HMGB1, thereby aggravating the progression of ALI and acute respiratory distress syndrome (ARDS)." (PMID 35720285, 2022).